MYH7 (myosin heavy chain 7)
Diseases named in the same sentence as MYH7 in open-access papers (continued):
Sharing a sentence is not in itself a finding about the gene and the disease.
hypertrophic cardiomyopathy (continued). "Furthermore, c.2609G>T p.(Arg870Leu) and c.52903C>T p.(Arg17635*) were identified in MYH7 (associated with hypertrophic cardiomyopathy) and TTN (associated with dilated cardiomyopathys), respectively." (PMID 40699671, 2025). "The disease-causing myosin variant (MYH7-403Q) is linked to hypertrophic cardiomyopathy (HCM)." (PMID 41282547, 2025). "MYH7 are well-known causes of hypertrophic cardiomyopathy (HCM)." (PMID 40423332, 2025). "Mutations in MYH7 are linked to muscular dystrophy and hypertrophic cardiomyopathy." (PMID 39796173, 2025). "A variant of unknown significance in MYH7, p.Met659Ile (c.1977G>A), was previously identified in several genetic screenings of hypertrophic cardiomyopathy patients." (PMID 40556978, 2025). "Similarly, patients with combined DMD and myosin heavy chain 7 (MYH7) variants demonstrate unique mixed-cardiac phenotypes, showing features of both dilated and hypertrophic cardiomyopathy." (PMID 40134720, 2025). "Mutations in MYH7 are a common cause of hypertrophic cardiomyopathy, and end-stage hearts exhibited changes in MYH7/MYH6 ratio, which may be affected by DNMT3A." (PMID 39596076, 2024). "We observed significant upregulation of heart disease markers Myh7, Xirp2, and Acta1, as well as alterations in proteins associated with hypertrophic cardiomyopathy and cardiac muscle contraction, indicating the successful establishment of the MI and TAC models." (PMID 39502510, 2024). "Missense mutations in myosin heavy chain 7 (MYH7) are a common cause of hypertrophic cardiomyopathy (HCM), but the molecular mechanisms underlying MYH7-based HCM remain unclear." (PMID 36902340, 2023). "Mutations in MYH6 and MYH7 are associated with hypertrophic cardiomyopathy." (PMID 37701139, 2023). "Furthermore, the MYH7 gene, specifically associated with hypertrophic cardiomyopathy, also exhibited a significant increase following CIH exposure." (PMID 38132482, 2023). "The second group, novel PTVs, comprised 27 variants in 27 carriers and yielded four individuals: three with hypobetalipoproteinemia, all with various novel truncating mutations in APOB, and one individual with hypertrophic cardiomyopathy and frameshift deletion in MYH7." (PMID 34691145, 2021). "To date, more than 400 hypertrophic cardiomyopathy-associated mutations have been described in Myh7 gene, and patients with likely pathogenic or pathogenic variation in Myh7 gene have a higher rate of incident atrial fibrillation independent of clinical and echocardiographic factors." (PMID 34266473, 2021). "Autosomal dominant MYH7 mutation has been reported in patients with hypertrophic cardiomyopathy." (PMID 33484326, 2021). "Onset of a hypertrophic cardiomyopathy in one member was a further “red flag” that could have directed the genetic analysis towards MYH7 and thus reduced the diagnostic “odyssey” for this family." (PMID 27005958, 2016). "Mutation location in the MYH7 gene and changes in amino acid composition may have a crucial negative impact on the outcome of the disease in patients with hypertrophic cardiomyopathy." (PMID 21674835, 2011). "In patients with hypertrophic cardiomyopathy, an increase in β‐myosin heavy chain expression, that is, a higher MYH7 to MYH6 ratio, is commonly observed." (PMID 39981966, 2025). "The most frequently pathogenic variants in hypertrophic cardiomyopathy are MYBPC3 and MYH7, which together account for approximately 70% of cases." (PMID 41019439, 2025). "Rare diseases (monogenic), such as hypertrophic cardiomyopathy (e.g., MYBPC3, MYH7 mutations), dilated cardiomyopathy (LMNA, RBM20), or inherited arrhythmias (KCNQ1, RYR2), are often caused by single, well-characterized mutations." (PMID 40465697, 2025). "Hypertrophic cardiomyopathy (HCM) is an inherited cardiomyopathy often caused by pathogenic variants in MYBPC3 and MYH7, encoding myosin‐binding protein C3 and myosin heavy chain 7, respectively." (PMID 40613316, 2025).
hypertrophic cardiomyopathy (continued). "It is estimated that ~83% of hypertrophic cardiomyopathy patients exhibit mutations in the myosin-encoding genes MYBPC3 and MYH7." (PMID 40869375, 2025). "Structural disorders include hypertrophic cardiomyopathy (HCM), the most prevalent cause, accounting for 35% of confirmed cases in the U.S., characterized by mutations in genes like MYH7, MYBPC3, and TNNT2." (PMID 40724525, 2025). "Among hypertrophic cardiomyopathy-related genes, high phenotypic expression of Myh7 affects the myocardial mechanical function, Nppa expression reactivated in the ventricles is a marker of heart disease, and elevated BNP (Nppb) is a hallmark of heart failure." (PMID 38628440, 2024). "In the cases of dilated cardiomyopathy, cardiac muscle contraction, and hypertrophic cardiomyopathy (B), seven downregulated proteins were enriched, including Myl2, Myl3, Myh7, Atp2a1, Tpm1, Tpm2, and Ttn." (PMID 39861068, 2024). "ΔEPORE mice also expressed more than two-fold increased expression of hypertrophic cardiomyopathy-related genes, Acta1, Myh7, Nppa, and Nppb." (PMID 38628440, 2024). "Pathogenic variants in genes such as MYH7, TPM1, and TNNI3 that encode parts of the cardiac sarcomere cause muscle diseases that affect the heart, such as dilated cardiomyopathy and hypertrophic cardiomyopathy." (PMID 37457373, 2023). "Mutations of MYH7 and MYL3 have been reported in various myopathies such as hypertrophic cardiomyopathy." (PMID 38173464, 2023). "Thesewere associated with increased right VAs scores and induction rates, andincreased myocardial expression of Myh7 which is the most frequentlymutated gene in hypertrophic cardiomyopathy." (PMID 39077026, 2023). "Specifically, pediatric patients had more MYH7 and MYL3 variants in hypertrophic cardiomyopathy, and fewer TTN truncating variants in dilated cardiomyopathy." (PMID 37477868, 2023). "For example, MYH7, a gene described to be responsible for hypertrophic cardiomyopathy, was highly expressed in heart than in other tissues." (PMID 36217153, 2022). "One was a carrier of a MYH7 (familial hypertrophic cardiomyopathy, MIM 192600) missense variant, whose grandfather was diagnosed with hypertrophic cardiomyopathy." (PMID 36143288, 2022). "Hypertrophic cardiomyopathy (HCM) is an inherited disorder of the myocardium, and pathogenic mutations in the sarcomere genes myosin heavy chain 7 (MYH7) and myosin-binding protein C (MYBPC3) explain 60%–70% of observed clinical cases." (PMID 32344918, 2020). "Pharmacological approaches for DA should be informed by research in hypertrophic cardiomyopathy on the closely related cardiac myosin heavy chain gene, MYH7." (PMID 33016623, 2020). "In general, histological analyses in our cohort suggest an overlap with the spectrum of congenital myopathies as already indicated by description of central cores in MYH7-related hypertrophic cardiomyopathy and by several familial reports with FTD." (PMID 27387980, 2016). "Earlier genetic analyses revealed crucial insights into the main genetic culprits of these disorders, such as SCN5A for Brugada syndrome, and MYH7 and MYBPC3 for hypertrophic cardiomyopathy, which have revolutionized diagnosis, risk stratification, and medical management." (PMID 41465121, 2025). "Although there is no exact proportion of people with hypertrophic cardiomyopathy, patients with MYH7 R453C mutation have been reported as an inherited familial HCM worldwide while HCM patients carrying the MYH6 R453C variant were rare." (PMID 38862020, 2024). "“Hypertrophic cardiomyopathy” in the signal pathway was followed with the p.adjust value of 1.10×10-3 and the corresponding collective action gene set with mutations included 8 genes: IGF1, CACNA1S, MYH7, IL6, TTN, CACNB2, LAMA2, DMD." (PMID 37876543, 2023).
hypertrophic cardiomyopathy (continued). "Myh7 pathogenic variantscan cause a variety of cardiac diseases, including hypertrophic cardiomyopathy,DCM, left ventricular noncompaction cardiomyopathy, congenital fiber-typedisproportion, and myosin myopathy." (PMID 39077026, 2023). "In addition, many genes with changes in both m6A modification and gene expression are related to cardiac processes, such as Myh7, bmp4 and Ttn, which were shown to be related to hypertrophic cardiomyopathy." (PMID 35953789, 2022). "MYH7 has been described primarily in the context of hypertrophic cardiomyopathy in humans." (PMID 34356106, 2021). "Although genetic testing identified MYH7 gene mutations in both the proband and his father, these mutations are primarily associated with hypertrophic cardiomyopathy and dilated cardiomyopathy, and neither the proband nor his family members exhibited related clinical symptoms." (PMID 40303613, 2025). "Central cores on muscle biopsy have been observed in a group of patients with hypertrophic cardiomyopathy secondary to mutations in the beta-myosin heavy chain (MYH7) gene, however, these patients typically do not have associated muscle weakness or any other features of typical CCD." (PMID 17504518, 2007). "Other conditions which may feature central cores on muscle biopsy include hypertrophic cardiomyopathy (HCM) associated with missense mutations in the β-myosin heavychain gene, MYH7; in contrast to CCD, muscle weakness is, however, exceptional and there are no associated musculoskeletal deformities." (PMID 17504518, 2007). "The present study comprised sarcomeric genotyping of the three most commonly involved sarcomeric genes: MYBPC3, MYH7, and TNNT2 in 192 unrelated Egyptian hypertrophic cardiomyopathy (HCM) index patients." (PMID 23233322, 2013). "In hypertrophic cardiomyopathy (HCM), MYBPC3, MYH7, PRKAG2, RAF1, and RBM20 were prevalent." (PMID 41341110, 2025). "High-dose EPO also increased heart failure-associated genes such as Cdk8, Nox4, S100A, and SERCA2a, and hypertrophic cardiomyopathy-related genes such as Acta1, Myh7, Nppa, and Nppb in male WT mice but not in ΔEPORE male mice." (PMID 38628440, 2024). "Next, our KEGG analysis showed that transcripts up-regulated in the mutant cardiomyocytes were related to hypertrophic cardiomyopathy (ACTC1, MYL2, MYL3), Ca2+-dynamics regulatory pathway (ATP2B4, CACNA1C, CAMK2B, PLN), as well as cardiac-muscle contraction transcripts (ACTC1, MYH7, TNNI3, TNNT2)." (PMID 35784482, 2022). "Of these proteins, MYH7, TPM1 and MYOZ2 are known to be important in hypertrophic cardiomyopathy, and may play a similar role in HFpEF." (PMID 36093146, 2022).
heart failure (93 papers, 2010 to 2026). Inability of the heart to pump blood at an adequate rate to meet tissue metabolic requirements. "Cardiac contractility is impaired in mice with the MYH7 Q315R variant, and these metabolic findings are similar to those of known metabolic changes in heart failure." (PMID 41237118, 2025). "MYH7 mutation can lead to severe hypertrophic and dilated cardiomyopathy, which can eventually lead to heart failure." (PMID 40029616, 2025). "The worsening of cardiac remodeling and progression to heart failure triggered by isoproterenol stress supports the idea that the MYH7 Q315R variant mice exhibit a phenotype typical of HFpEF." (PMID 41237118, 2025). "Analysis of gene function revealed that CACNA1S, ATP2A3, and MYH7 were involved in cardiac muscle contraction and adrenergic signaling in cardiomyocytes, both of which are associated with heart failure and other diseases." (PMID 40029616, 2025). "This case highlights the diverse array of cardiac pathologies that can present with MYH7 gene variants and reviews an extensive work-up for this unusual presentation of heart failure in a young patient." (PMID 38813076, 2024). "The upregulation of Myh7 has been linked to a transition from hypertrophy to heart failure, marked by an increase in Myh7 mRNA and protein levels, particularly pronounced in severe cardiac stress." (PMID 38892126, 2024). "Regression analysis also favored these findings by showing that the carriers of MYH7 rs121913642 C allele were at ~2 folds higher risk of heart failure compared to MYH7 rs121913642 T allele carriers." (PMID 36140722, 2022). "The current study also indicated that MYH7 variant rs121913642 (Ser532Pro) increases the risk of heart failure in patients from Punjab, Pakistan." (PMID 36140722, 2022). "RT-qPCR analysis revealed that cardiac fetal genes including Acta1, Myh7, Nppb, and Nppa, which are associated with heart failure, were significantly increased in GsαCMKO mice." (PMID 34907172, 2021). "Cardiac toxicity at a cumulative dose of 12 mg/kg (3 mg/kg/week for 4 weeks) was confirmed by histopathological lesions and altered expression of genomic indicators associated to contraction performance (Myh6, Myh7) and heart failure (Ankrd1/CARP, Nppb)." (PMID 22859947, 2012). "Therefore, developing treatments that specifically target mitochondrial impairments linked to MYH7 variants offers a promising direction for heart failure management." (PMID 41237118, 2025). "Moreover, the MYH7 rs121913642 TC genotype increases the risk of heart failure and is significantly associated with serum concentrations of cTnI and CK-MB." (PMID 36140722, 2022). "Mutations in MYH7 have been studied and are found to be strongly associated with heart failure." (PMID 36140722, 2022). "Finally, analysis of mRNA expression in hearts from Akita mice showed an upregulation in expression of a number of genes associated with heart failure, including Nppa, Nppb, Gdf15, Fgf21 and Myh7." (PMID 32979176, 2020). "Increasing the Myh7/Myh6 ratio by overexpression of Myh7 has been shown to cause heart failure." (PMID 33260869, 2020). "Heart failure-associated fetal gene program is also characterized by upregulation of β-MyHC (Myh7), the dominant isoform of myosin heavy chain in the fetal cardiomyocytes, and a down regulation of α-MyHC (Myh6), the dominant isoform in the adult cardiomyocytes." (PMID 30811446, 2019). "Compared with the control group, the heart failure marker genes Nppa and Nppb; fibrosis-related gene Postn, and hypertrophy-related gene Myh7 were upregulated in the ISO/PE group." (PMID 40129768, 2025). "Correspondingly, the mRNA levels of heart failure biomarkers, including atrial natriuretic peptide (Anp), brain natriuretic peptide (Bnp), and myosin‐7 (Myh7), were markedly lower in the DOX‐treated EBBP‐overexpressing mice." (PMID 40491313, 2025).
heart failure (continued). "Among these, Nppa, a heart failure marker, was upregulated in both the MYH7 Q315R/+ and MYH7 Q315R/Q315R groups compared to the wild-type group." (PMID 41237118, 2025). "Myh6 and Myh7 are genes that encode the α- and β-myosin heavy chain (MHC), respectively, and can serve as a marker for heart failure-related sarcomeric remodelling." (PMID 40517248, 2025). "Compared with the ISO group, the heart failure marker genes NPPa and NPPb; fibrosis-related gene Postn and hypertrophy-related gene Myh7 also showed clear upregulation in the ISO/PE group." (PMID 40129768, 2025). "These EVs contributed to preventing maladaptive remodeling, inhibiting the onset of fibrosis, and decreasing the expression of heart failure molecular indicators (such as myosin heavy chain isoforms Myh6/Myh7 ratio)." (PMID 38892376, 2024). "Myh6 (α-myosin heavy chain) and Myh7 (β-myosin heavy chain) are differentially regulated in heart failure, and mRNA levels for these genes were oppositely modulated by the TM54 transgene and AAV9sc.PBD treatment." (PMID 38572067, 2024). "OM is a small-molecule activator that was developed for the treatment of heart failure which increases the calcium sensitivity of force production by binding to cardiac myosin (MYH7)." (PMID 38634969, 2024). "Conversely, the inner regions showed elevated levels of myosin heavy chain-7 (Myh7) and ANP (Nppa), markers linked to cardiac stress and hypertrophy, similar to findings from single-cell RNA-seq studies in the same heart failure TAC model." (PMID 38892126, 2024). "Myosin heavy chain 7 (Myh7) is a newly characterized marker for heart failure; in vivo overexpression studies of Myh7 resulted in cardiac dilation, and cardiac failure." (PMID 37891673, 2023). "Detailed results of the current study demonstrated higher frequency of MYH7 rs121913642 TC in patients with heart failure." (PMID 36140722, 2022). "The switch from Myh6 to Myh7 expression is an important feature of specific sets of GE related to heart failure per se." (PMID 33260869, 2020). "Taken together, gross clinical examination unveiled the terminal stage of PH reliably and was accompanied by foetal gene re‐expression (Nppb, Myh7), an event correlating with experimental cardiac failure." (PMID 32395887, 2020). "SFRP4, as the other activated upstream regulator, inhibited TNNT2 and MYH7, which contributed to the development of heart failure and arrhythmia." (PMID 32423033, 2020). "The expression of heart failure markers including Nppa, Nppb and Myh7 in mice treated with Yy1 was significantly reduced compared to that in DCM mice treated with EGFP control." (PMID 31705051, 2019). "Quantitative PCR (qPCR) analysis of csPLA-Tg myocardium showed that there was reduced mRNA expression of Myh6 and increases in Myh7, Nppa, and Nppb mRNA, consistent with heart failure." (PMID 31622279, 2019). "Omecamtiv mecarbil (OM) is a selective small-molecule activator of cardiac myosin (Myh7 or β-MHC) that was developed as a treatment for heart failure." (PMID 31721788, 2019). "The expression levels of certain genes in the heart failure stage varied considerably (e.g., Nppa, Myh7, and Xirp2)." (PMID 30375404, 2018). "As well as being elevated in modeled hypertrophic settings, we also observed paralleled expression between LRRC2 and MYH7, an established biomarker of heart failure, in the human heart." (PMID 28158196, 2017). "AAV-HDAC1/2 also restored repression of slow twitch sarcomere genes Acta1 and Myh7, and reduced expression of the heart failure marker Nppa." (PMID 28394251, 2017). "As in the neonatal Gata4/6 loss-of-function experiment, Myh7 and Nppa were highly upregulated in GATA4/6 knockout hearts, while Myh6 was highly downregulated, consistent with changes observed in heart failure." (PMID 26023924, 2015). "In this study, we investigated the mechanism of T3/TR-induced negative regulation of the MYH7 gene, the expression of which is a molecular marker for heart failure." (PMID 24781449, 2014).